FOXP3 (forkhead box P3)
Diseases named in the same sentence as FOXP3 in open-access papers (continued):
Sharing a sentence is not in itself a finding about the gene and the disease.
tumor (continued). "A population of spleenic CD4+CD69+, but CD25− and FoxP3−, T cells with regulatory activity has been described in tumor-bearing mice." (PMID 22319577, 2012). "Accordingly, CD3 and CD163 specific staining data indicate that tumor infiltration by FOXP3+ cells is highly correlated with infiltration by CD3+ cells." (PMID 22471961, 2012). "Regulatory T cells (CD4+CD25+FoxP3+; Tregs) do not only inhibit autoreactive T cells to maintain immunological self-tolerance, but also anti-tumor immune responses in the tumor microenvironment." (PMID 22674057, 2012). "The tumor-infiltrating FoxP3+ T cells largely lack CD62L and CCR7, two trafficking receptors required for T cell migration into secondary lymphoid tissues." (PMID 22292042, 2012). "We found that FoxP3+ and CD8+ densities in tumor stroma were independently associated with patient survival in multivariable models." (PMID 22879926, 2012). "Taken together, these results demonstrate that immunomodulation with SA-4-1BBL is effective in preventing the conversion of conventional CD4+ T cells into CD4+CD25+FoxP3+ T cells in a tumor microenvironment." (PMID 22870329, 2012). "Analysis of Treg subsets revealed a Cy-sensitive CD4+Foxp3+CD25low tumor-seeking migratory phenotype, characteristic of effector/memory Tregs, and capable of high avidity T cell suppression." (PMID 22359647, 2012). "Instead, the ratio of CD3+ lymphocytes to FOXP3+ Treg was a better predictor of disease-free survival than tumor stage or lymph node spread, and high intratumoral CD8+ to Treg ratios also correlate to better survival." (PMID 22319577, 2012). "The percentage of Treg cells (CD4+Foxp3+T cells) in the tumor microenvironment was similar at different time points." (PMID 23140567, 2012). "In this regard, most T cells that were once FoxP3+ T cells retain their expression of FoxP3 in tumors, suggesting that tumor-infiltrating FoxP3+ T cells are highly stable in tumors." (PMID 22292042, 2012). "The percentages of CD4+CD25+Foxp3+ Treg cells infiltrated in tumor sites were dramatically decreased after WGP treatment, and were again reversed to high levels after GITR blocking treatment." (PMID 23077535, 2012). "FoxP3+ Tregs can suppress host-mediated anti-tumor immunity and tumor-specific cytotoxicity, suggesting that Treg depletion is a potential therapeutic strategy." (PMID 22879926, 2012). "As compared with the others, patients with higher percentages of FOXP3-positive Tregs on initial tumor biopsy have a significantly longer OS (p = 0.003)." (PMID 22151904, 2011). "The relationship between CD4, CD8 or Foxp3 positive cells with clinico-pathological variables was examined (differentiation, lymphatic invasion, tumour margin, tumour site, vascular invasion)." (PMID 21864372, 2011). "A direct link between the presence of Tregs and the progression of ovarian cancer has been demonstrated, where tumour FOXP3+ Tregs suppressed tumour specific immunity and contributed to reduced survival." (PMID 21818290, 2011). "The Foxp3+ Tregs in PTs, TDLNs, benign disease, and normal adjacent tissues were detected using IHC staining method." (PMID 22110525, 2011). "∼40% of the CD4+ cells present in the tumor were Foxp3+ Tregs, demonstrating a selective recruitment of inhibitory cells to the tumor as a portion of total leukocytes compared to the TDLN." (PMID 21731676, 2011). "There was a correlation between clinical regression and increased MART-1-specific CD8+ T cells and a decrease in CD4+FoxP3+ Tregs at the tumor site." (PMID 24213115, 2011). "In murine models, depletion of CD4+FoxP3+ Tregs enhances tumor rejection and improves therapeutic responses to cancer vaccines by promoting the function of CD8+ cytotoxic T lymphocytes." (PMID 24213115, 2011). "FoxP3+ Treg-cells begin to infiltrate into the incipient tumor lesion at a very early stage of tumor development." (PMID 21559338, 2011). "Meanwhile, we observed the attraction of tumor cells to FoxP3+ cells by secreting massive CCL20 (right)." (PMID 21935436, 2011).
tumor (continued). "The authors showed that multiple vaccinations increased the absolute number of CD4+Foxp3+ Tregs in the peripheral blood and in the spleens, which decreased the therapeutic efficacy of splenocytes when adoptively transferred into tumor-bearing mice." (PMID 21859450, 2011). "In these latter patients, clone-specific TCR-Vβ-chain antibodies were used to demonstrate that these FOXP3+CD25- cells are monoclonal CTCL tumor cells." (PMID 22151904, 2011). "Using multivariable analysis, tumor FoxP3+ Treg density was found to be an independent prognostic factor of overall survival (Hazard Ratio, 2.4; P = 0.013) and disease-free survival (Hazard Ratio, 2.0; P = 0.041)." (PMID 21935436, 2011). "Specific depletion of T reg cells using mice that express diphtheria toxin receptor under the control of the Foxp3 locus induced tumor regression." (PMID 21533081, 2011). "Our data demonstrated that GP reduced the proportion of Treg cells and decreased Foxp3 expression in Treg cells, and up-regulated Th1/Th2 cytokine ratio in serum in H22 hepatocarcinoma tumor bearing mice, which might partially cause the inhibition of tumor growth." (PMID 21963624, 2011). "As observed in PBMC of human patients, FoxP3 (Red staining) was abundantly expressed in tumor tissue derived from mice treated with MNU and H. pylori compared with normal colon of untreated mice or IgG control staining." (PMID 21559338, 2011). "The correlation between IDO expression levels and the densities of Foxp3+ Tregs in the primary tumor tissues (PTs) and tumor-draining lymph nodes (TDLNs), as well as various clinical and pathological indexes of the patients were investigated." (PMID 22110525, 2011). "The positive effect of FoxP3+ T cells has been proposed to be a result of their effects on other T cells that are promoting tumour growth." (PMID 21864372, 2011). "Evidence supporting an essential role for FoxP3+ Treg-cells in tumor immune evasion comes from studies that eliminated Treg-cells before tumor challenge." (PMID 21559338, 2011). "The biology CD4 T cell population in these Pmel mice have not been studied; we noted an increased percent expression of Foxp3 in CD4s from both control and tumor-bearing mice, and to a comparable degree." (PMID 22112546, 2011). "Most importantly, macrophage depletion by administration of DT led to a marked reduction in the number of tumor-infiltrating FoxP3+ Treg-cells." (PMID 21559338, 2011). "FOXP3+CD25- CTCL tumor cells show a highly demethylated status of the Foxp3 gene locus similar to Tregs, and they are functionally able to suppress IL-2 mRNA induction in TCR-stimulated conventional T cells." (PMID 22151904, 2011). "Although further studies are required before these markers can be employed, the present results suggest that assessment of SPARC and FOXP3 expression in tumour tissue should improve the prognostic classification of stage II and III CRC." (PMID 21818290, 2011). "In the current study, the results show that mRNA expression of Foxp3 in the lymph nodes of GP-treated tumor-bearing mice is decreased." (PMID 21963624, 2011). "The hypoxia-associated marker carbonic anhydrase IX (CA9) and double FOXP3/CXCR4 staining were performed on sections from a subset of these cancers including 10 basal-like and 11 luminal cancers matched for tumour grade." (PMID 21521526, 2011). "Previous studies have concentrated on characterizing T cell populations in the primary tumour where T cells with regulatory effect (Foxp3+ Tregs) have been identified as both enhancing and diminishing anti-tumour immune responses." (PMID 21864372, 2011). "We confirmed that a significantly higher frequency of CD4+FoxP3+ Treg-cells were present in the tumor, as compared to normal colon (mean 9.095%±1.038% vs mean 0.478%±0.095%, p<0.0001)." (PMID 21559338, 2011). "This nanogram concentration level of TGFβ in the tumor microenvironment should be adequate to induce Foxp3." (PMID 22112546, 2011).
tumor (continued). "To determine quantity and distribution of Tregs in tumor tissue, we performed immunohistochemical staining of FoxP3 in paraffin-embedded tissue from HCC patients (Group 1, n = 293)." (PMID 21935436, 2011). "In conclusion, the percentage and function of tumor-infiltrating FOXP3+ T cells predicts different survival." (PMID 22151904, 2011). "GATA3 was low in the bladder of tumor-bearing mice at day 7, and FOXP3 was increased indicating the presence of suppressor cells." (PMID 22013484, 2011). "We observed that this approach (LRAST) increases the systemic anti-tumor immune response and initially reduces the number of FoxP3+CD25+CD4+ Tregs." (PMID 21859450, 2011). "In the present study, we aimed to evaluate the subsets of TIL including CTL, activated CTL, Treg, and Th17 cells by CD8/Foxp3, GrB/Foxp3 and Foxp3/IL-17 double IHC staining in 106 paraffin-embedded NPC tumor tissues." (PMID 20064222, 2010). "Positive CD4, CD3, CD8, CD68 and Foxp3 cells were detected in 33/33 (100%) tumor samples and their mean number were similar between the two patient groups." (PMID 20591136, 2010). "We found that the number of CD8 and Foxp3 double positive TIL was positively correlated with tumor lymphoid nodal metastasis in NPC patients (P = 0.006) (the same as CD8+TILs)." (PMID 20064222, 2010). "Treg cells have been shown to negatively affect tumor immunity as the depletion of CD4+CD25+FoxP3+ Treg from tumor tissue and the TSLN has been shown to facilitate tumor rejection." (PMID 20946663, 2010). "Our present study found that the tumor infiltrating Foxp3+ Treg cell was an independent favorable factor for the T stage and for survival in the NPC patients, while the tumor infiltrating CD8+, GrB+ or IL-17+ cells was not an independent factor for survival." (PMID 20064222, 2010). "The recruitment of Foxp3-positive regulatory T cells (Treg) into tumor likely represents one of the mechanisms by which malignant cells evade host immune response." (PMID 20591136, 2010). "Our study identifies for the first time the tumor infiltrating Foxp3+ TIL as an independent favorable factor in the prognosis of NPC patients, especially for the patients with late-stage diseases." (PMID 20064222, 2010). "In order to understand the role of the CD8+Foxp3+Treg and GrB+Foxp3+ activated Treg cell subsets in NPC tumor tissues, we double stained CD8 and Foxp3, and GrB and Foxp3." (PMID 20064222, 2010). "Results of this study also identified several other types of TILs within the tumor center as having a positive impact on prognosis, for example FoxP3." (PMID 21179245, 2010). "Regulatory T (Treg) cells, a subset of CD4+CD25+Foxp3+ T lymphocytes, are mediators with the functional ability to regulate/suppress tumour immunity." (PMID 19935800, 2009). "We demonstrate a relative expansion of FoxP3+ regulatory T-cells (Treg) and of cytotoxic T-cells among tumour infitrating T-cells." (PMID 19698134, 2009). "The tissue specific induction of Foxp3+ cells in lung tissues prior to tumor development suggests that NNK-induced Foxp3+ T cells provide a permissive environment for the development of K-Ras-driven lung tumors." (PMID 19330036, 2009). "Eliminating Foxp3+ cells by crossing K-RasLA2 mice to scurfy mice nonetheless decreased lung tumorigenesis, which shows that even though fewer tumor infiltrating lymphocytes were induced in the K-RasLA2 model, Foxp3+ cells still played a critical role." (PMID 19330036, 2009). "Histological analysis of resected specimens showed a significant increase in CD8+ tumour-infiltrating T-cells and decreased expression of FOXP3 and IL-10 in patients who took indomethacin." (PMID 19384299, 2009). "There was a trend towards improved DFS rates for patients with an increased infiltration of FoxP3+-TIL in the primary tumour with 86% vs. 63% (p = 0.27) as well as FoxP3+-TIL in N+ nodes with 84% vs. 53% (p = 0.17)." (PMID 19698134, 2009).
tumor (continued). "In contrast to CD8+ T cells, several studies have indicated that tumor-infiltrating CD25+FoxP3+ T cells (referred to as regulatory T cells or Tregs) are associated with decreased survival." (PMID 19641607, 2009). "In vitro tumour-derived prostaglandin E2 (PGE2) increases FOXP3 expression and Treg inhibitory activity." (PMID 19384299, 2009). "Because activated macrophages and tumor cells can recruit Foxp3+ cells, it is possible that the role attributed to alveolar macrophages was mediated through activation of Foxp3+ cells." (PMID 19330036, 2009). "The precise role of regulatory T cells in cancer outcomes warrants further consideration given that several groups are attempting to enhance tumor immunity by depleting FoxP3+ Tregs from cancer patients, including EOC patients." (PMID 19641607, 2009). "Using this approach, we show that, as a proportion of CD3+ T-cells, tumour infiltrating CD8+ and Granzyme B+ cytotoxic T-cells as well as FoxP3+ Treg were relatively enriched in primary and metastatic tumours when compared to uninvolved lymphoid tissue." (PMID 19698134, 2009). "Similar to the results for MHC class I, the expression of MHC class II in tumor epithelium was positively associated with various T cell markers, including CD3, CD4, CD8, CD45RO, TIA-1, Granzyme B, CD25 and FoxP3." (PMID 19641607, 2009). "Patients with high versus low stromal CD68+/FoxP3+ cell ratios in primary tumour displayed median survivals of 32 and 55 months, respectively (p = 0.008)." (PMID 19732435, 2009). "We have also reported that soluble factors derived from tumor cells promoted the generation of CD4+ CD25high Foxp3+ Treg and inhibited CTL induction by fusions." (PMID 20182533, 2009). "The density of FOXP3-positive cells in tumour stroma was significantly higher in unmetastasised CRCs compared with tumours with lymph node or distant metastases." (PMID 18985040, 2008). "The biological significance of these findings warrants further investigation in the context of tumor immune escape, and especially under the light of current anti-cancer efforts interfering with Foxp3 expression." (PMID 18430198, 2008). "In contrast, the presence of tumor-infiltrating CD25+FoxP3+ T cells in EOC is correlated with inferior survival." (PMID 18923710, 2008). "A direct link between the presence of Tregs and progression of ovarian carcinoma has been demonstrated where human tumor FOXP3+ Tregs were found to suppress tumor specific immunity and contribute to reduced survival of these patients." (PMID 18294387, 2008). "The prevalence of Foxp3+ cells was significantly increased in the tumour lesion compared to normal gastric tissue." (PMID 18087278, 2008). "We provide unequivocal evidence that Foxp3 is expressed both at the transcript and protein level by tumor cells of various types." (PMID 18430198, 2008). "We have demonstrated that FOXP3+ Tregs infiltrating tumor tissues correlates significantly with important bad prognostic factors: large tumor size (P = .029), high histological grade (P < .001) and estrogen receptor negative status (P = .010)." (PMID 18294387, 2008). "Autoantibodies to NY-ESO-1 were associated with increased tumor-infiltrating CD8+, CD4+ and FoxP3+ cells." (PMID 18923710, 2008). "In all tumours, the number of infiltrating FOXP3-positive cells was higher in the tumour stroma than in the epithelium." (PMID 18985040, 2008). "Methylcholanthrene-induced tumours were removed from mice and examined histologically for Tregs by staining sections with Abs specific for FOXP3 and CD4." (PMID 17565340, 2007). "We did however observe that IFNγ−/− mice, when challenged with MCA, demonstrate a reduction of the percentage of CD4+FOXP3+ Tregs within tumours and TDLN." (PMID 17565340, 2007). "We surmised that immune surveillance would be hampered by the inhibitory effect of naturally occurring FoxP3+ regulatory T cells, a population of T cells shown to be present at an increased frequency in a variety of human tumours." (PMID 17565340, 2007).
tumor (continued). "This was confirmed by partial ablation of FoxP3+ regulatory T-cell activity, which resulted in a marked reduction in tumour incidence." (PMID 17565340, 2007). "A wealth of evidence obtained using mouse models indicates that CD4+CD25+FOXP3+ regulatory T cells (Treg) maintain peripheral tolerance to self-antigens and also inhibit anti-tumor immune responses." (PMID 17205133, 2006). "Additional IHC staining for CD8+, CD4+, and FOXP3 + T cells demonstrated immune cell infiltration into mouse tumor that received 4‐1BBL/IL‐12 nanoparticles, and little immune cell infiltration into mouse tumor that received luciferase nanoparticles." (PMID 41496905, 2026). "Flow cytometry and western blot revealed that SSG can increase the proportion of CD8+ central memory T cells, reduce the proportion of CD8+ effector memory T cells, reduce the proportion of CD4+CD25+Foxp3+ Treg cells, and play a role in regulating the tumor microenvironment." (PMID 41993133, 2026). "Additionally, analyses using the TIMER and GEPIA databases further showed that Integrin α L expression was positively correlated with both the expression of Foxp3 (a canonical marker of Treg cells) and tumor TNM stage (a key indicator of tumor progression)." (PMID 41601682, 2026). "TME profiling revealed an "immune-cold" phenotype characterized by low densities of CD4+, CD8+, and FOXP3+ T cells, CD19+ and CD20+ B cells, CD56+ and CD57+ NK cells, and CD163+ tumor-associated macrophages, alongside minimal checkpoint activity and focal fibroblast activation." (PMID 42058215, 2026). "Furthermore, increased expression of SIGLEC15 was associated with higher levels of PD-1, FOXP3 and, CXCR1, and lower levels of CD69 in tumor tissues." (PMID 41158758, 2026). "Following sequential immunohistochemical staining for CD4+ and Foxp3+ T-cells, whole-slide scans were analyzed using QuPath software to quantify T-cells in the tumor center (TC), inner margin (IM), outer margin (OM), and peritumor zone (PT) of both pCRC and LM." (PMID 42216261, 2026). "Furthermore, the lowest rate of Treg cells (CD3+CD4+Foxp3+) was observed in the UP+2 Gy group, suggesting that significantly fewer Treg cells remained in tumor tissues." (PMID 41355957, 2026). "This stage-specific modulation underscores the complexity of FOXP3’s role and suggests that its prognostic relevance may depend not only on expression levels but also on timing within the tumor’s evolutionary trajectory." (PMID 40806346, 2025). "It was shown that MCPyV infection could be induced in the MCC tumor CD3, CD8, FoxP3, and PD-L1 positive cells, confirming the fact that the viral infection increases the tumor’s immunogenicity." (PMID 40227764, 2025). "In addition, it can reduce the transcription of FOXP3 and inhibit Treg cells, thereby alleviating tumor immunosuppression." (PMID 41561762, 2025). "Elevated FOXP3 and PD-1 expressions correlate significantly with advanced disease stages and poorer prognoses, highlighting their central roles in immune suppression and tumor progression." (PMID 41375087, 2025). "FOXP3 is a marker for Tregs, contributing to an immunosuppressive environment within the tumor." (PMID 40735045, 2025). "The reduction of tumor growth with anti-VEGF was associated with increased infiltration of CD8+ effector T cells and CAR-T cells and reduced infiltration of immunosuppressive regulatory T cells (FOXP3+CD4+T cells)." (PMID 40894718, 2025). "We observed a decrease of Treg cells (CD45+CD4+FoxP3+) in tumor-draining lymph nodes (tdLN) in NPc-Rel-treated mice compared to PBS-treated mice; however, the percentages of the tdLN T helper cells (CD45+CD4+) and cytotoxic T cells (CD45+CD8+) were similar among all groups." (PMID 40134427, 2025). "Moreover, our study provided a detailed analysis of the expression patterns of FOXP3 in ccRCC and its specific impact on the tumor immune environment, discussing its potential as a therapeutic target." (PMID 39883234, 2025).